IRF5 (interferon regulatory factor 5)
Diseases named in the same sentence as IRF5 in open-access papers (continued):
Sharing a sentence is not in itself a finding about the gene and the disease.
Hyperglycemia (5 papers, 2020 to 2022). An increased concentration of glucose in the blood. "In conclusion, we found that IRF5 upregulation in T2D patients’ monocytes was associated with indicators of hyperglycemia and inflammation." (PMID 32806763, 2020). "IRF5 expression in macrophages was induced/upregulated (p < 0.05) by hypoglycemia (3 mM/L), persistent hyperglycemia (15 mM/L–25 mM/L), and RIH/glucose fluctuations (3–15 mM/L) as compared to normoglycemia (5 mM/L)." (PMID 32806763, 2020). "This may be due to the function of IRF5 being more inflammatory over time or when supported by other microenvironmental cues (e.g. hypoxia, cytokines, hyperglycaemia)." (PMID 36042203, 2022). "In further elucidating the underlying mechanisms of M1-like macrophage polarization and inflammatory cytokines/chemokine production in response to RIH, we found that hyperglycemia-driven changes were counteracted as the expression of IRF5 was silenced in macrophages." (PMID 32806763, 2020). "IRF5 gene expression was significantly upregulated in macrophages cultured under hypoglycemia (p = 0.0003), persistent medium hyperglycemia (p = 0.003), and persistent strong hyperglycemia (p = 0.01) as compared to normoglycemic control." (PMID 32806763, 2020). "The molecular mechanisms linking hyperglycaemia and cellular glucose metabolism directly to an IRF5‐dependent cytokine storm have recently been described in the case of influenza A virus (IAV) infection, of which some mechanisms may be shared with COVID‐19." (PMID 32816392, 2020). "Evident findings revealed that IRF5 expression could be induced by persistent hyperglycemia, repetitive intermittent hyperglycemia and glucose fluctuations and the contribution of daily postprandial glucose peaks after meals to the SARS-CoV-2 replication was proposed." (PMID 33297431, 2020). "Interestingly, IRF5 expression was also upregulated in macrophages that were cultured under the RIH or glucose fluctuations as compared to normoglycemic control (p = 0.02), which was comparable (p > 0.05) to IRF5 expression under the persistent hyperglycemia at 15 mM/L and 25 mM/L concentrations." (PMID 32806763, 2020). "Recently, we reported significant correlations between the increased adipose IRF5 expression and the body mass index, inflammatory markers, and hyperglycemia in nondiabetic overweight/obese individuals." (PMID 32806763, 2020).
ischemic stroke (5 papers, 2018 to 2025). A stroke disorder caused by obstruction of blood flow to the brain, due to thrombotic (local blood clot formation) or embolic (due to a blood clot or other material traveling from another site) event. "In addition, other paralogs of IRF6, such as IRF4, IRF5, IRF8, and IRF9, have been linked to neuronal survival following ischemic stroke." (PMID 40149423, 2025). "Moreover, miR-31 from ADSC-derived extracellular vesicles (EVs) has been shown to downregulate the expression of TRAF6 and IRF5, leading to reduced ischemic stroke-induced neuronal damage." (PMID 35454994, 2022). "In microglial IRF5 CKO mice, the absence of the IRF5 signal leads to increased expression of IRF4, enhanced M2 activation, reduced pro-inflammatory response, and improved outcomes in ischemic stroke." (PMID 39649720, 2024).
lymphoma (5 papers, 2009 to 2025). A malignant (clonal) proliferation of B- lymphocytes or T- lymphocytes which involves the lymph nodes, bone marrow and/or extranodal sites. "The frequencies of the IRF5 polymorphism in these lymphomas were higher or similar to those (49%) described in healthy German blood donors." (PMID 23028731, 2012). "It remains to be investigated whether any of the IRF5 haplotypes or SNPs is associated with lymphoma development." (PMID 23028731, 2012). "Similarly, the LOR1a retrotransposon activates interferon regulatory factor 5 (IRF5) transcription in the same lymphoma type, promoting overexpression of this factor and supporting cancer cell proliferation." (PMID 40328728, 2025). "In this study, we identified a G202C (position relative to start codon) missense mutation (Ala68Pro) in DNA binding domain of IRF-5 (IRF-5(P68) in tumor or transform B and T cell lines and peripheral blood from chronic lymphocytic leukemia (CLL) and adult T-cell leukemia/lymphoma (ATL) patients." (PMID 19430534, 2009).
pancreatic cancer (5 papers, 2013 to 2022). "Recent studies, however, reported that the MYC-associated zinc finger protein (MAZ) and the interferon regulatory factor 5 (IRF5) are direct activators of Zfp217 transcription, contributing to, respectively, prostate cancer (PCa) and pancreatic cancer aggressiveness." (PMID 36551531, 2022).
Splenomegaly (5 papers, 2011 to 2021). Abnormal increased size of the spleen. "IRF-5 is largely responsible for promoting inflammatory cell infiltration into the spleen, which ultimately results in splenomegaly." (PMID 32038622, 2019). "CD11c-specific Irf5−/− mice are more resistant to L. donovani infection, suggesting that the induction of splenomegaly is detrimental to the host." (PMID 32038622, 2019). "The degree of lymphadenopathy and splenomegaly was substantially reduced in the IRF5−/− MRL/lpr mice with a concomitant reduction in total spleen cell number." (PMID 25076492, 2014). "Therefore, we evaluated the effect of heterozygous deletion of IRF5 in B cells on splenomegaly and found that it was markedly reduced and to the same extent as that seen in global IRF5-heterozygous FcγRIIB−/−Yaa mice." (PMID 34197340, 2021). "Next, we wanted to determine whether IRF-5 expression in myeloid cells was at all required to induce splenomegaly that is typically present following L. donovani infection." (PMID 32038622, 2019). "Indeed, Irf5−/− mice fail to develop splenomegaly and to develop protective Th1 responses following L. donovani infection." (PMID 32038622, 2019). "Notably, as with splenomegaly, no impact on T cell activation was seen in FcγRIIB−/−Yaa mice expressing Mb1cre alone or the IRF5-floxed allele alone compared with FcγRIIB−/−Yaa mice." (PMID 34197340, 2021). "Taken together, our results imply that IRF-5 expression in myeloid cells is not required for promoting inflammatory cell infiltration, Th1 responses, and splenomegaly during chronic experimental VL." (PMID 32038622, 2019). "In conclusion, we demonstrated that Irf5 expression in CD11c+ cells is required for the development of splenomegaly but does not affect the development or the maintenance of protective Th1 responses during experimental VL." (PMID 32038622, 2019). "We also demonstrate that Irf5 expression in CD11c+ cells is essential for inducing splenomegaly, but it is not required for the development or maintenance of parasite-specific IFNγ-producing CD4 T cells." (PMID 32038622, 2019). "failed to induce splenomegaly in Irf5-/- mice, which is characteristic for L. donovani infection in WT mice." (PMID 21253574, 2011). "However, in IRF5-/- mice and in myeloïd CD11c specific IRF5-/- mice, Leishmania failed to induce splenomegaly which seems to be detrimental to the host." (PMID 33898331, 2021). "Indeed, L. donovani-infected Irf5−/− mice not only failed to develop splenomegaly, but also displayed severely impaired parasite-specific Th1 responses." (PMID 32038622, 2019). "Moreover, in Irf5-/- mice we could not observe any splenomegaly, which is a typical symptom of VL in WT mice." (PMID 21253574, 2011).
Cerebral ischemia (4 papers, 2020 to 2023). Restriction of arterial blood supply to the brain associated with insufficient oxygenation to support the metabolic requirements of the tissue. "Thus, microglial expression of interferon regulatory factor 5 (IRF5) has been linked to proinflammatory responses to cerebral ischemia." (PMID 36818562, 2023). "Conversely, reducing IRF4 expression can lead to increased IRF5 expression, promote M1-type activation, exacerbate the inflammatory response, and lead to worse outcomes in cerebral ischemia." (PMID 37361996, 2023). "IRF5 and IRF4 balance each other, and reducing the expression of IRF5 can promote M2-type activation, increase IRF4 expression, inhibit the inflammatory response, and improve outcomes in cerebral ischemia." (PMID 37361996, 2023).
colorectal cancer (4 papers, 2012 to 2025). A primary or metastatic malignant neoplasm that affects the colon or rectum. "Our study aimed to examine potentially functional genetic variants in interferon regulatory factor 3 (IRF3), IRF5, IRF7, type I and type II IFN and their receptor genes with respect to colorectal cancer (CRC) risk and clinical outcome." (PMID 25350395, 2014).
HIV-1 infection (4 papers, 2009 to 2025). The type species of lentivirus and the etiologic agent of acquired immunodeficiency syndrome (AIDS). "Here, we investigate whether IRF-5 also contributes to memory CD4+ T cell loss during HIV-1 infection." (PMID 37227774, 2023). "To visualize IRF5 activation in response to HIV-1 infection in macrophages, we utilized immunofluorescence and confocal microscopy." (PMID 40493408, 2025). "Since IRF5 expression was elevated in macrophages from older donors, we next sought to assess age-related differences in innate immune response to HIV-1 infection." (PMID 40493408, 2025). "HIV-1 infection results in nuclear translocation of IRF5 in THP-1/PMA macrophages." (PMID 40493408, 2025). "Since the Fas/FasL pathway is involved in memory CD4+ T cell death in HIV-1 infection, we next assessed whether the IRF-5–CPP mix could block Fas-mediated apoptosis in memory CD4+ T cells from ART HIV-1+ individuals." (PMID 37227774, 2023). "Since it was previously reported that memory CD4+ T cell death during HIV-1 infection is Fas-mediated, and IRF-5 is required for Fas-induced apoptosis, we set out to investigate whether Fas was downstream of IRF-5 in human CD4+ T cells." (PMID 37227774, 2023). "Our analysis also found that IRF-5 gene expression could be induced upon HIV-1 infection in macrophages but in lower abundance." (PMID 19404407, 2009). "Since HIV-1 infection is characterized by a strong inflammatory environment, tissue disruption, and upregulation of TLR7 in CD4+ T cells, we wondered whether the TLR7/IRF-5 pathway was involved in impairing memory CD4+ T cell homeostasis during HIV-1 infection." (PMID 37227774, 2023). "Upon HIV-1 infection of MDMs, we also observed a higher level of ISG induction in MDMs from older donors, including IRF5, as well as several known IRF5-responsive genes, such as CXCL16, CCL5, and CD80." (PMID 40493408, 2025). "These upregulated genes were primarily ISGs, including IRF5 and IRF7, as well as several known IRF5 target genes, including CCL5, CXCL16, and IL23A, suggesting that MDMs from older individuals display an enhanced IRF5-dependent innate immune response to HIV-1 infection." (PMID 40493408, 2025). "In contrast to IP-10, expression of IFN-β was robustly attenuated by knockdown of IRF3, IRF5, or IRF7 expression in HIV-1–infected MDMs, suggesting a selective and nonredundant role of IRF5 in mediating a proinflammatory response to HIV-1 infection in macrophages." (PMID 40493408, 2025).
ischemia (4 papers, 2018 to 2023). A hypoperfusion of the BLOOD through an organ or tissue caused by a PATHOLOGIC CONSTRICTION or obstruction of its BLOOD VESSELS, or an absence of BLOOD CIRCULATION. "In summary, the present study explored several key molecular mechanisms for IRF5/IRF4 to regulate microglial response to ischemia." (PMID 33573200, 2021).
primary biliary cirrhosis (4 papers, 2011 to 2018). "In addition, high-throughput genetic studies of primary biliary cirrhosis (PBC) associated IRF5 and IRF8 with the pathogenicity of autoimmune liver diseases." (PMID 29531645, 2018).
visceral leishmaniasis (4 papers, 2011 to 2023). A severe form of leishmaniasis characterized by irregular bouts of fever, substantial weight loss, swelling of the spleen and liver, and anemia (which may be serious). "We have previously reported that activation of IRF-5 in murine IFN-γ+CD4+ T cells leads to cell death during chronic visceral leishmaniasis." (PMID 37227774, 2023). "We have recently identified the transcription factor IFN regulatory factor 5 (IRF-5) as a detrimental player in the survival of CD4+ T cells during chronic visceral leishmaniasis." (PMID 37227774, 2023). "The increased production of IFNγ by CD8+ lymphocytes that we observed after IRF5 silencing was particularly interesting, in view of another recent study relating to chronic visceral leishmaniasis in mice." (PMID 33369221, 2021). "In this study, we investigated the role of IRF-5 in myeloid cells during experimental visceral leishmaniasis (VL)." (PMID 32038622, 2019). "In this study, we used the experimental model of visceral leishmaniasis to investigate the role of IRF-5 in the generation of Th1 responses and in the formation of Th1-type liver granulomas in Leishmania donovani infected mice." (PMID 21253574, 2011).
Alzheimer disease (3 papers, 2019 to 2021). A progressive, neurodegenerative disease characterized by loss of function and death of nerve cells in several areas of the brain leading to loss of cognitive function such as memory and language. "In summary, this study we have also identified important genes (NRG1, NEDD9, IRF5, IFI35, STAT1, STAT2, JAK2, IL3RA), and alterations in biological processes and pathways that may be associated with Alzheimer’s Disease." (PMID 34484988, 2021).
emphysema (3 papers, 2020 to 2026). "A previous study showed increased IRF5 expression in the lungs of cigarette smoke (CS)-induced emphysema." (PMID 41639423, 2026). "Our findings highlight IRF5 as a critical regulator of emphysema pathogenesis via NLRP3-mediated pyroptosis and Ly6Chigh-expressing immune cells." (PMID 41639423, 2026). "The correlation between IRF5 levels and emphysema in humans was also evaluated." (PMID 41639423, 2026). "Here we investigated the function of IRF5 in emphysema using Irf5-knockout (KO) mice." (PMID 41639423, 2026). "The relative mRNA levels of TNF-α, IFN-γ, IL-8, IL-18, IRF-5, and TGF-β increased in the emphysema mice." (PMID 32681029, 2020). "Importantly, the mRNA levels of IL-1β, TNF-α, IL-8, IRF-5, IL-18, IFN-γ, TGF-β, matrix metalloproteinase-9 (MMP-9), and MMP-12 were decreased in the FMT-treated emphysema group compared with the emphysema group." (PMID 32681029, 2020). "Moreover, the mRNA expression of other representative proinflammatory mediators, including IL-1β, tumor necrosis factor-α (TNF-α), IL-8, IL-18, and immune modulators, such as interferon regulatory factor-5 (IRF-5) and transforming growth factor-β (TGF-β), was increased in emphysema mice." (PMID 32681029, 2020).
fungal infection (3 papers, 2014 to 2019). "In fact, Dectin-1, known to recognize β-glucans of fungal cell wall, is widely expressed by DCs and macrophages and the activation of IRF5 by the Dectin-1-Syk pathway has been implicated in the induction of type I interferon-β (IFN-β) gene upon fungal infection." (PMID 25149452, 2014). "During fungal infection, Dectin-1 affects macrophage polarization by activating IRF5 in the Dectin-Syk pathway." (PMID 28614714, 2017).
Hypertension (3 papers, 2014 to 2025). The presence of chronic increased pressure in the systemic arterial system. "Ingenuity Pathway Analysis (IPA) identified crucial pathways and regulatory networks, highlighting IRF5 as a key regulatory factor in high-salt DOCA-induced hypertension or inflammatory conditions." (PMID 40332339, 2025). "SNP rs4728142, an intergenic variant mapped to genes IRF5 and KCP, has been reported to be associated with hypertension in previous GWAS28." (PMID 36380121, 2022). "Collectively, these findings indicate that under high-salt DOCA-induced hypertension conditions, IRF5 acts as a key regulatory factor, likely interacting with STAT1 and STAT2 within the same regulatory network, contributing to the pathological processes in SSH." (PMID 40332339, 2025). "In this study, we identified aortic inflammation, including remodeling, fibrosis, and apoptosis, in a DOCA-induced SSH mouse model and investigated the role of IRF5 in regulating vascular inflammation, which points to a new direction for future immunotherapy in hypertension." (PMID 40332339, 2025).
invasive breast carcinoma (3 papers, 2015 to 2025). A carcinoma that infiltrates the breast parenchyma. "Human in vitro and murine in vivo models of invasive breast cancer confirmed an important role for IRF5 in regulating cell motility, invasion and/or metastasis; yet, the mechanism(s) by which this occurs is not known." (PMID 25649192, 2015). "IRF5, MAP2K2 (MEK2), and ZBTB7B were significantly overexpressed (p < 0.05) in invasive breast cancer blood samples but not in DCIS blood samples." (PMID 37445737, 2023).
myositis (3 papers, 2018 to 2024). "In large scale case-control studies in a Chinese Han population using candidate gene approach, CCL21, a myositis susceptibility gene in Caucasians, was found to associate with PM or PM-associated ILD, TNFAIP3 and IRF5 with myositis or myositis-associated ILD, and PLCL1 with DM and DM-associated ILD." (PMID 29854780, 2018). "Next, we colocalized IIM signals that overlapped IMD signals, and found seven potentially novel myositis associations mapped to immune-related genes, including BLK, IRF5/TNPO3, and ITK/HAVCR2, implicating a role for both B and T cells in IIM." (PMID 39044428, 2024). "IRF5 could repeatedly be detected in plasma aliquots from a myositis patient using IP-MS utilizing peptide exact mass (high-resolution m/z) and retention time." (PMID 31156624, 2019).
nephritis (3 papers, 2010 to 2022). Inflammation of renal tissue. "Patients in the RF-IgM/SSA/SSB subgroup showed lower frequency of nephritis (20%) compared to IRF5 low (43%) and IRF5 high (48%) subgroups." (PMID 31156624, 2019). "To determine if SLE-related genetic variants associate specifically with nephritis in SLE patients, we genotyped up to nine variants from the IRF5, STAT4 genes and the TRAF1-C5 locus." (PMID 20479942, 2010). "To test this hypothesis we compared the genotype, allelic and haplotype frequencies from IRF5, STAT4 and TRAF1-C5 polymorphisms between IgAN patients and healthy controls, and SLE patients with and without nephritis, from TGFB1 polymorphisms between SLE patients and healthy controls." (PMID 20479942, 2010).
Renal insufficiency (3 papers, 2013 to 2019). A reduction in the level of performance of the kidneys in areas of function comprising the concentration of urine, removal of wastes, the maintenance of electrolyte balance, homeostasis of blood pressure, and calcium metabolism. "But the presented pattern showed significant decline in severe LN group, suggesting IRF5 diminishing role with the perpetuation of renal insufficiency." (PMID 31507612, 2019). "The highest serum BUN levels were seen in the IRF5+/+ MRL/lpr mice with 5 of the 12 mice, having serum BUN levels greater than 30 mg/dl indicative of marked renal failure." (PMID 25076492, 2014).
rheumatic diseases (3 papers, 2014 to 2024). "The IRF5 gene, important in immune regulation, is linked to rheumatic diseases like SLE, RA, and SS due to its influence on type I interferons and pro-inflammatory cytokines." (PMID 38675400, 2024). "Several genetic studies have described the relevance of multiple single-nucleotide polymorphisms (SNPs) of the IRF5 gene in different rheumatic disorders, such as RA and lupus erythematosus." (PMID 25011482, 2014). "Recently, researchers have described an association between multiple single-nucleotide polymorphisms of the IRF5 gene and some rheumatic disorders." (PMID 25011482, 2014). "IRF5 gene polymorphism is a well-known risk factor in SLE and in several other rheumatic diseases." (PMID 31156624, 2019).